HOTTIP (HOXA distal transcript antisense RNA)
Diseases named in the same sentence as HOTTIP in open-access papers (continued):
Sharing a sentence is not in itself a finding about the gene and the disease.
fibrosis (2 papers, 2019 to 2024). the formation of excess fibrous connective tissue in an organ or tissue in a reparative or reactive process. "Importantly, HOTTIP was noticeably upregulated in patients with pulmonary fibrosis and enhanced lung tissue fibrosis via miR-744-5p/PTBP1." (PMID 38238652, 2024).
Hirschsprung disease (2 papers, 2022 to 2025). Hirschsprung disease (HSCR) is a congenital intestinal motility disorder that is characterized by signs of intestinal obstruction due to the presence of an aganglionic segment of variable extent in the terminal part of the colon. "Another study which focused on Hirschsprung disease has suggested a negative association between the lncRNAs HOTTIP rs3807598 C > G and risk of Hirschsprung disease." (PMID 40959107, 2025). "In addition to its inhibitory effect in cancers, HOTTIP was also found to decrease the proliferation and cell migration in Hirschsprung disease." (PMID 35210436, 2022).
lung squamous cell carcinoma (2 papers, 2019 to 2022). "Moreover, HOTTIP showed prognostic value in lung squamous cell carcinoma and kidney renal clear cell carcinoma." (PMID 31032351, 2019).
oral cancer (2 papers, 2019 to 2025). "In conclusion, our study first revealed the associations of HOTTIP polymorphisms to oral cancer disease susceptibility and clinical statuses." (PMID 40959107, 2025). "For HOTTIP rs2067087, in male oral cancer patients, a significant association was found between HOTTIP rs2067087 “CG+GG” genotype and metastasis [OR (95% CI): 0.115 (0.013-0.985); p = 0.017]." (PMID 40959107, 2025). "In this study, we investigated the associations between SNPs in the HOTTIP gene and both oral cancer susceptibility and clinicopathological characteristics." (PMID 40959107, 2025). "In this study, we discovered the associations between the HOTTIP SNPs and oral cancer." (PMID 40959107, 2025). "However, the associations of HOTTIP polymorphisms to oral cancer progression and clinicopathologic characteristics remained unclear." (PMID 40959107, 2025). "Therefore, it might be the ageing microenvironment and the vital regulatory role of HOTTIP ceRNA which contribute to the better prognosis of HOTTIP rs3807598 and rs2067087 polymorphisms in male oral cancer patients with age ≥ 60 in our study." (PMID 40959107, 2025). "Nevertheless, previous studies have consistently shown that HOTTIP is significantly upregulated in oral cancer tissues compared to adjacent normal tissues, supporting its potential oncogenic role in oral cancer." (PMID 40959107, 2025). "HOTTIP and HCG22 can interact with hsa-mir-21 in the ceRNA network, which promote oral cancer invasion via the Wnt/β-catenin pathway." (PMID 31681590, 2019).
papillary thyroid carcinoma (2 papers, 2021 to 2023). "Specifically, miR-637 was indicated to be regulated by HOTTIP in papillary thyroid carcinoma." (PMID 34290981, 2021).
rheumatoid arthritis (2 papers, 2022 to 2024). A chronic, systemic autoimmune disorder characterized by inflammation in the synovial membranes and articular surfaces. "For example, HOTTIP participates in acute gouty arthritis through miR-101-3p/BRD4 and is associated with rheumatoid arthritis." (PMID 38238652, 2024).
squamous cell carcinoma (2 papers, 2019 to 2025). A carcinoma arising from squamous epithelial cells. "Patients with squamous cell carcinoma had significantly higher levels of HOTTIP than those with adenocarcinoma (p = 0.007)." (PMID 30819158, 2019). "HOTTIP was expressed in all tumor samples and was overexpressed in squamous cell carcinoma (p = 0.007) and in smokers (p = 0.018)." (PMID 30819158, 2019). "In our cohort, tumor HOTTIP levels were significantly overexpressed in squamous cell carcinoma compared to adenocarcinoma." (PMID 30819158, 2019). "Additionally, we validated our findings on the prognostic value of HOTTIP levels in another patient population using TGCA data and the TANRIC webtool, showing that HOTTIP impacts prognosis in NSCLC patients with adenocarcinoma but not in those with squamous cell carcinoma." (PMID 30819158, 2019).
thyroid cancer (2 papers, 2025). "Similarly, HOTTIP is an oncogene that is also associated with downregulating miR-744-5p, which normally inhibits c-myc and promotes apoptosis; therefore, c-myc downregulation allows for thyroid cancer resistance to apoptosis." (PMID 41154428, 2025).
acute respiratory distress syndrome (1 paper, 2025). Progressive and life-threatening pulmonary distress in the absence of an underlying pulmonary condition, usually following major trauma or surgery. "Increased levels of HOTTIP may serve as a diagnostic biomarker for sepsis-associated acute respiratory distress syndrome (ARDS) and potentially forecast short-term mortality risk." (PMID 39912974, 2025).
benign pancreatic tumour (1 paper, 2016). "And H19, HOTAIR, HOTTIP, MALAT1, and PVT1 levels did not significantly differ between NPT and benign pancreatic tumours (BPT) tissues (p values were 0.522, 0.759, 0.200, 0.631, and 1.000, respectively)." (PMID 27028998, 2016).
cervical cancer (1 paper, 2019). A primary or metastatic malignant neoplasm involving the cervix. "HOTTIP was shown to be downregulated in cervical cancer but upregulated in colon adenocarcinoma, rectum adenocarcinoma, and stomach adenocarcinoma." (PMID 31032351, 2019).
chronic pancreatitis (1 paper, 2015). A chronic inflammatory process causing damage and fibrosis of the pancreatic parenchyma. "Twenty seven lncRNAs including HOTTIP, were upregulated more than 10-fold in PDAC compared with chronic pancreatitis tissues." (PMID 25889214, 2015).
diabetic nephropathy (1 paper, 2024). "Persistent down-regulation of HOTTIP expression effectively attenuates inflammation induced by high glucose and up-regulation of fibrillar-associated proteins in diabetic nephropathy." (PMID 38238652, 2024). "The suppression of HOTTIP also typically alleviated neuroinflammatory damage in Parkinson’s and high glucose-induced inflammation in diabetic nephropathy." (PMID 38238652, 2024).
diabetic retinopathy (1 paper, 2025). "A study investigated the expression levels of lncRNAs, including HOTTIP, in the serum of patients with varying stages of diabetic retinopathy." (PMID 40616679, 2025). "The findings indicated that HOTTIP expression increased with the severity of diabetic retinopathy, suggesting its potential as a biomarker for this complication." (PMID 40616679, 2025).
esophageal cancer (1 paper, 2025). A primary or metastatic malignant neoplasm involving the esophagus. "It was discovered that by favorably activating the ATP-binding cassette sub-family G member 2 (ABCG2) protein, HOTTIP controls medication resistance in esophageal cancer." (PMID 40616679, 2025). "By using real-time polymerase chain reaction (RT-PCR) and following treatment with varying dosages of adriamycin (ADM) in cells, the serum level of HOTTIP in patients with esophageal cancer was determined in order to investigate its function in drug resistance." (PMID 40616679, 2025). "In cancers like esophageal cancer, targeting HOTTIP-mediated pathways (e.g., ABCG2) could enhance chemotherapeutic efficacy." (PMID 40616679, 2025).
fibroids (1 paper, 2025). "The results showed that LINC02433, LINC01449, SNHG12, H19, and HOTTIP were elevated in premenopausal fibroids, but remained unchanged in postmenopausal ones, while ZEB2-AS1 displayed higher levels only in postmenopausal fibroids." (PMID 40862769, 2025).
gouty arthritis (1 paper, 2024). "Moreover, decreased HOTTIP significantly suppressed the release of pro‐inflammatory factors IL‐1β and IL‐8 in macrophages during acute gouty arthritis." (PMID 38363110, 2024).
hepatitis B (1 paper, 2024). "Additionally, dysregulated HOTTIP is involved in oral mucosal inflammation, hepatitis B, and inflammation in systemic sclerotic disease." (PMID 38238652, 2024).
ovarian tumor (1 paper, 2021). "HOTTIP increased DDP resistance in ovarian tumor cells by miR-205 sponging and ZEB2 up regulation." (PMID 34593006, 2021). "There was a significant HOTTIP up regulation in DDP resistant ovarian tumor cells." (PMID 34593006, 2021).
Primary hyperaldosteronism (1 paper, 2016). A form of hyperaldosteronism caused by a defect within the adrenal gland. "Our identification and independent replication of variants in KCNK3, a gene implicated in primary hyperaldosteronism, as well as a variant in HOTTIP (HOXA-EVX1) suggest that further work to clarify the roles of these genes may be warranted." (PMID 27736895, 2016).
respiratory infection (1 paper, 2024). "HOTTIP levels (P < 0.001) can independently influence the development of ARDS, as well as COPD (P = 0.014), respiratory infection (P = 0.048), and higher CRP (P = 0.029)." (PMID 38238652, 2024).
retinoblastoma (1 paper, 2022). A malignant tumor that originates in the nuclear layer of the retina. "HOTTIP silencing triggers apoptosis of human retinoblastoma cells, while HOTTIP overexpression suppresses apoptosis." (PMID 36230902, 2022).
testicular cancer (1 paper, 2021). A primary or metastatic malignant neoplasm that affects the testis. "If its correlation with testicular cancer were to be further investigated, HOTTIP could represent an excellent biomarker." (PMID 33767982, 2021). "Both SPRY4-IT1 and HOTTIP were shown to increase testicular cancer proliferation, so their inhibition or downregulation could lead to a decrease of tumor aggressiveness and size." (PMID 33767982, 2021).
testicular embryonal carcinoma (1 paper, 2021). A malignant germ cell neoplasm arising from the testis. "In testicular embryonal carcinoma, HOTTIP was described to promote cell proliferation via the competitive binding to miR‐128‐3p." (PMID 33767982, 2021). "In fact, HOTTIP was found upregulated in testicular embryonal carcinoma cells compared to the control, and its knock-out in those cells resulted in a decrease of the proliferative rate." (PMID 33767982, 2021).
triple-negative breast carcinoma (1 paper, 2024). An invasive breast carcinoma which is negative for expression of estrogen receptor (ER), progesterone receptor (PR), and human epidermal growth factor receptor 2 (HER2). "OICR-9429 and molecule 7k were used to antagonize the lncRNA–WDR5 complex in MDA-MB-231 cells, a triple-negative breast cancer cell line, and the expression level of HOTTIP was studied." (PMID 38389889, 2024).
cancer (106 papers, 2015 to 2026). A tumor composed of atypical neoplastic, often pleomorphic cells that invade other tissues. "HOTTIP single nucleotide polymorphisms hold significant promise in personalized medicine by serving as biomarkers for cancer susceptibility, progression, and treatment response." (PMID 40616679, 2025). "A growing body of evidence indicates that dysregulation of HOTTIP is linked to a number of cancers and impacts the prognosis and survival of cancer patients but what are the normal physiological functions of HOTTIP in non-cancerous tissues?" (PMID 40616679, 2025). "Further studies on its dysregulation have linked HOTTIP to certain cancers, where its aberrant expression influences tumor by modulating key developmental pathways." (PMID 40616679, 2025). "For instance, lncRNAs such as UCA1 and HOTTIP have been implicated to play a promising role in carcinogenesis, cancer progression, and chemoresistance." (PMID 35586209, 2022). "This suggests that HOTTIP is not only involved in developmental processes but also enhances the effect of this lncRNA as a cancer-associated lncRNA considering its role as a signaling transmitter from higher-order chromosome conformation to chromatin coding." (PMID 34899344, 2021). "Many studies have reported that higher expression of HOTTIP is associated with positive lymph node metastasis and unfavorable prognosis in various cancer types." (PMID 32983633, 2020). "High HOTTIP expression was frequently reported to associate with poor clinical outcomes of cancer patients, including CRC." (PMID 32246818, 2020). "lncRNAs play an important role in cancer mainly via their associations with RNA-binding g proteins, which include HOTTIP, MaLAT1, H19, and HOTAIR." (PMID 31827401, 2019). "The association of HOTTIP SNPs with cancer susceptibility or prognosis has been preliminarily explored." (PMID 30940774, 2019). "Overexpression of HOXA genes, including HOTTIP, has been associated with a more aggressive phenotype in several cancers." (PMID 30819158, 2019). "Recently, increasing studies showed that aberrant expression of HOTTIP is associated with various cancers." (PMID 31681590, 2019). "The result demonstrated that cancer patients with high HOTTIP expression in tumor tissues were more susceptibility to develop LNM." (PMID 27806342, 2017). "This meta-analysis demonstrated that high HOTTIP expression in cancer patients is associated with poor clinical outcomes." (PMID 28938659, 2017). "Although HOTTIP was found to be significantly associated with the prognosis of cancer patients, some limitations in our meta-analysis should be mentioned." (PMID 27806342, 2017). "Many recent studies have indicated the associations of HOTTIP variants with cancer risk." (PMID 39049088, 2024). "Moreover, it has been revealed that HOTTIP up-regulation or MEG3 down-regulation is associated with cancer pathogenesis and progression." (PMID 39049088, 2024). "According to meta-analysis result, we observed that the high HOTTIP expression group might be associated with a worse survival in various carcinomas (pooled HR = 2.34, 95% CI 1.96–2.79, p < 0.0001)." (PMID 32566641, 2020). "The prognostic role of HOTTIP levels has been described in several cancers and analyzed in several meta-analyses, which concluded that high HOTTIP expression in cancer patients is associated with poor clinical outcome." (PMID 30819158, 2019). "Apart from prognostic value, HOTTIP also exhibited potential diagnostic value in cancers." (PMID 31032351, 2019). "Although the detailed mechanisms underlying the association of SNP in HOTTIP with cancer susceptibility are unclear, these findings could provide a new insight into understanding the genetic factors of cancer susceptibility and carcinogenesis." (PMID 29802154, 2018). "Moreover, there is increasing evidence about upregulated HOTTIP in various types of cancer tissues and that was associated with cancer progression and poor prognosis for PC." (PMID 28818070, 2017).
cancer (continued). "In conclusion, our meta-analysis suggests that the upregulation of HOTTIP is a risk factor for poor clinical outcomes in diverse cancers, and could serve as a potential prognostic biomarker." (PMID 28938659, 2017). "HOTTIP expression may also have an association with the prognosis and metastasis of human cancers." (PMID 40616679, 2025). "In fact, HOTTIP not only has been tested as a potential biomarker in several different tumors, and notably as a non-invasive biomarker in colorectal cancer, but several of its SNPs inside of it are associated to cancer susceptibility, prognosis, or therapy response." (PMID 33767982, 2021). "Furthermore, upregulation of HOTTIP was reported to be significantly associated with advanced clinical stages, positive lymph node metastasis, drug resistance, and poor clinical outcome of cancer patients." (PMID 31032351, 2019). "In various cancers, HOTTIP is frequently upregulated and plays a critical role in promoting tumor initiation and progression." (PMID 40624028, 2025). "Several differentially expressed lncRNA in fibroid from postmenopausal women have been shown to have oncogenic roles in different types of cancer including HOTTIP, SNHG12, CASC15, ZEB2-AS1." (PMID 40725045, 2025). "Future research should focus on developing precise tools to modulate HOTTIP activity, tailoring approaches to its context-specific roles in different cancers." (PMID 40616679, 2025). "In vitro and in vivo studies showed that HOTTIP induces proliferation, invasion, and gemcitabine resistance in cancer cells by modulating HOXA13 gene." (PMID 40352931, 2025). "It is worth noting that as a research team, we are currently working on a study stating HOTTIP SNPs’ roles in human cancer samples and other study on its genetic expression." (PMID 40616679, 2025). "HOTTIP overexpression further enhanced the ability of M1 exosomes to inhibit the proliferation, migration, and invasion of cancer cells, while inducing their apoptosis, indicating that HOTTIP is a key molecule in M1 exosomes." (PMID 40612677, 2025). "Specific examples include the following:Transcriptomics: RNA sequencing can quantify HOTTIP expression across different cancers and correlate its levels with clinical features such as tumor stage, metastasis, and response to therapy." (PMID 40616679, 2025). "These multi-omics strategies can refine HOTTIP’s role as a biomarker and therapeutic target, paving the way for personalized medicine tailored to its cancer- and context-specific functions." (PMID 40616679, 2025). "Recently, aberrant upregulation of HOTTIP has been observed in various types of cancer and found to be correlated with poor survival in cancer patients." (PMID 40624028, 2025). "Some studies have indicated the association of HOTTIP and MEG3 genetic polymorphisms with cancer susceptibility." (PMID 39049088, 2024). "In squamous cell carcinoma, M1-derived exosomes containing HOTTIP inhibit cancer cell proliferation and induce apoptosis by activating the TLR5/NF-κB pathway." (PMID 38473915, 2024). "CircRTN4 enhances the growth and metastasis of cancer cells by inhibiting miR-497-5p and increasing HOTTIP expression." (PMID 38559560, 2024). "Student’s ttest showed that the RNA level of HOTTIP in all the cancer tissues was much higher than that in normal tissues." (PMID 37392284, 2023). "This is consistent with studies that claim that HOTTIP is involved in the growth and invasion of cancer cells." (PMID 38186456, 2023).